LEAP2 (liver enriched antimicrobial peptide 2)
Diseases named in the same sentence as LEAP2 in open-access papers (continued):
Sharing a sentence is not in itself a finding about the gene and the disease.
Obesity (continued). "However, in the present study of obesity with T2DM, the decrease in fasting plasma LEAP2 with weight loss was delayed and attenuated after DJBL insertion compared to the SMM group." (PMID 39659543, 2024). "Plasma LEAP2 is increased, whereas plasma AG is decreased, in obesity [27, 29‐31]." (PMID 37287649, 2023). "For instance, in diet-induced obesity, not only is ghrelin reduced, but LEAP2 is elevated." (PMID 38099492, 2023). "Interestingly, they showed similar results in patients suffering from obesity and in mice fed with high-fat diet (i.e., increased plasma levels of LEAP-2)." (PMID 37867951, 2023). "Of note, it remains to be explored whether exogenous LEAP2 reduces food intake in animal models of impaired metabolic control, such as diet-induced obesity." (PMID 35492241, 2022). "In line with our data in ob/ob mice, we also found an anorexigenic effect of LEAP-2 in ghrelin-induced food intake in another obesity model, the DIO mice, which is in clear contrast to the leptin-resistant state observed in DIO mice and highlights its potential translational relevance." (PMID 35159134, 2022). "Functionally, the decrease in ghrelin/LEAP2 ratio in T2D patients may reduce the over-activation of GHSR in obesity to return to normal energy homeostasis." (PMID 35521798, 2022). "Together, these findings raise the possibility that LEAP2 might constitute a clinically relevant pharmacological target for the treatment of obesity." (PMID 35492241, 2022). "LEAP-2 can help prevent ghrelin-induced adiposity making it a potential therapeutic for obesity." (PMID 35454071, 2022). "Additionally, neurological dysfunction of the liver-expressed antimicrobial peptide 2 (LEAP-2) and its effects on the ‘hunger hormone’ ghrelin have also been highlighted as possible contributors towards the development of obesity." (PMID 35203552, 2022). "In addition, plasma LEAP2 was found to be positively correlated with some adverse metabolic parameters related to obesity, including BMI, body fat percentage, HOMA-IR, fasting blood glucose and serum triglyceride, VAT volume, and IHCL content." (PMID 36235843, 2022). "Hence, these data showed that the central overexpression of LEAP2 in the ARC protected mice against HFD-induced obesity and related metabolic disorders." (PMID 36387867, 2022). "LEAP-2 may have diverse roles in the development of obesity at different ages, which should be a direction for further studies." (PMID 34512549, 2021). "This may suggest that also in the case of obesity and hyperglycemia the regulation of Leap2 expression and eCBome signaling might be two unrelated phenomena, and not controlled in a coordinated manner by gut dysbiosis." (PMID 35011234, 2021). "According to available literature data, the regulatory mechanism of LEAP-2 and ghrelin in obesity during childhood may be inconsistent with that in adults." (PMID 34512549, 2021). "Since hyperinsulinemia occurring in obesity significantly deteriorates insulin resistant states, LEAP-2 knockdown may pull down the excessive insulin secretion, thereby improve insulin sensitivity." (PMID 34512549, 2021). "It remains to be clarified whether the gut microbiota-eCBome axis is involved in the control of intestinal LEAP2 levels, especially during obesity and hyperglycemia, where and confirmed here, all the members of this triangle undergo adaptive regulation." (PMID 35011234, 2021). "In summary, the results obtained in animal models of glucose intolerance and obesity suggest that ileal Leap2 expression may represent an early adaptive response aimed at counteracting dysmetabolism." (PMID 35011234, 2021). "Severe obesity is often accompanied by impaired ghrelin signaling, i.e., ghrelin resistance, and a recent study showed that obesity could increase the expression of LEAP2 mRNA in mice liver and induce both ghrelin and LEAP2 resistance in mice." (PMID 41488138, 2025).
Obesity (continued). "However, many issues, such as the efficacy of LEAP2 as a pharmacological target in the treatment of obesity, its possible role in hedonic eating behaviors, and the changes in its levels depending on different types of bariatric surgery, are still poorly understood." (PMID 40870497, 2025). "Moreover, LEAP2 levels appear to fluctuate based on factors such as gender, developmental stage, and even interventions like bariatric surgery, which is known for its role in managing obesity and diabetes." (PMID 39796232, 2025). "However, in the current study of men and women without obesity, higher BMI was associated with lower postprandial increases in plasma LEAP2." (PMID 37287649, 2023). "Additionally, the Ghrelin/LEAP-2 ratio could be studied in prevalent disorders that occur during pregnancy, such as obesity and diabetes." (PMID 36076912, 2022). "Therefore, it would be interesting to investigate whether LEAP2 KO animals or patients with reduced LEAP2 plasma levels present more severe obesity." (PMID 35050161, 2022). "In terms of the biological actions, in 2019, Mani and colleagues revealed that plasma level of LEAP-2 fluctuated in opposite to that of ghrelin according to metabolic status, and was positively correlated with body mass index (BMI) and many metabolic parameters of obesity." (PMID 34512549, 2021). "Liver-expressed antimicrobial peptide-2 (LEAP-2), a ghrelin receptor antagonist, has been connected to obesity and liver fat buildup in adults, but pediatric data are limited." (PMID 41226108, 2025). "In diet-induced obesity (DIO) mice, LEAP2 levels were significantly higher compared to the control group and were positively correlated with fat mass and body weight." (PMID 40214973, 2025). "In the present study, in the SMM group with obesity and T2DM, BMI positively correlated with fasting plasma LEAP2 across all visits, both for absolute values and decreases from baseline visit." (PMID 39659543, 2024). "Thus the discovery of the endogenous inverse agonist LEAP2 may reveal potential therapeutic targets for gastric hunger-related diseases, including type 2 diabetes and obesity, as it interacts with gastric hunger and is expressed at elevated levels after RYGB surgery." (PMID 36936164, 2023). "Recently discovered liver-expressed antimicrobial peptide 2 (LEAP2), an endogenous antagonist of ghrelin, is suggested as a promising candidate for the treatment of obesity." (PMID 36834794, 2023). "Circulating levels of liver-enriched antimicrobial peptide 2 (LEAP2), a ghrelin receptor antagonist, decrease under caloric restriction and increase in obesity." (PMID 35187383, 2022). "Finally, we investigated whether, and how, intestinal Leap2 expression is altered in mouse models of obesity/type 2 diabetes and how such alterations relate to those of the eCBome in the same models, where profound gut microbiota perturbations, sometimes referred to as dysbiosis, also exist." (PMID 35011234, 2021). "Weight loss after RYGB surgery for obesity without/with T2DM reduced fasting and/or postprandial plasma LEAP2 at 3 to 24 months after 16% to 31% weight loss." (PMID 39659543, 2024). "These correlational findings are consistent with a role for postprandial increases in plasma LEAP2 in suppressing human eating behavior in adults without obesity." (PMID 37287649, 2023). "Since then, LEAP-2 has been considered as a signal for energy surplus and an efficient regulator of energy balance, therefore has fostered emerging research on LEAP-2’s anti-obesity potent." (PMID 34512549, 2021). "Other diseases, including diabetes, cardiovascular diseases, and cancer, are highly related to obesity, therefore are likely to interact with LEAP-2 although has not been investigated yet." (PMID 34512549, 2021). "Unlike ghrelin, LEAP2 levels tend to be elevated in obesity." (PMID 40870497, 2025).
Obesity (continued). "Comparing results across different human studies (overall 3 without obesity, 6 with obesity, including the present study), there was a suggestion that the absolute postprandial increase in plasma LEAP2 is proportional to the preload fixed meal energy intake (rS = +0.59; P = .17)." (PMID 39659543, 2024). "However, medications to lower plasma glucose and improve insulin resistance (including metformin and dapagliflozin) in adults with overweight/obesity and prediabetes did not decrease fasting plasma LEAP2 over 13 weeks." (PMID 39659543, 2024). "However, in the current study of adults without obesity, the lack of positive correlations suggests that postprandial increases in plasma LEAP2 are not driven by postprandial increases in plasma glucose, serum insulin, or triglycerides." (PMID 37287649, 2023). "In mice without obesity and humans with obesity, plasma glucose positively correlated with plasma LEAP2 across fasting and postprandial time points, suggesting that glucose might stimulate LEAP2 secretion after meals in humans." (PMID 37287649, 2023). "In the only human study to date, exogenous full-length LEAP2 infusion in men without obesity, when fed to produce mildly supraphysiological plasma LEAP2 concentrations, acutely reduced food intake but not appetite ratings, supporting a stimulatory role of GHSR1a signaling on human food intake." (PMID 37287649, 2023). "However, LEAP2 regulation in this tissue has not yet been investigated, nor have its potential interactions therein with two major and inter-related players in obesity, i.e., the eCBome and the gut mBIome." (PMID 35011234, 2021). "In a previous study, postprandial increases in plasma LEAP2 positively correlated with BMI across a combined cohort of women with normal weight and obesity, although this did not appear to be present in those without obesity alone, and no adults with overweight were included." (PMID 37287649, 2023). "However, acute exogenous LEAP2 administration in men without obesity, to increase plasma LEAP2 to ∼2.6 times normal when fed, did not alter plasma AG, though this could be a dose or duration effect rather than species difference." (PMID 37287649, 2023).
diabetes (11 papers, 2020 to 2026). "The next logical step would be to conduct more experiments using diabetes models and to use these findings as a key argument for the necessity of testing LEAP2 as a therapeutic agent for diabetic patients." (PMID 39796232, 2025). "Existing research on other classes of animals has not yet fully addressed critical topics such as the relationship between LEAP2, nutrition, body mass, energy changes, and diabetes." (PMID 39796232, 2025). "In this review, We focus on the feeding-induced hepatokines, including Adropin, Manf, Leap2 and Pcsk9, Which participate in the occurrence and development of diabetes." (PMID 36936164, 2023). "Oral glucose administration also causes rises in LEAP2 levels and the LEAP2/acyl-ghrelin molar ratio while type 1 diabetes mellitus (T1DM) causes rises in LEAP2 levels without changes in the LEAP2/ghrelin ratio." (PMID 39796232, 2025). "In summary, LEAP2 can improve diabetes by inhibiting brain intake-related energy metabolism." (PMID 36936164, 2023). "In addition, participants with metabolic disorders such as diabetes, hyperlipidemia, and hypercholesterolemia, as well as thyroid and hypothalamic disorders that may potentially affect LEAP2 regulation, were excluded." (PMID 37212281, 2023).
Hepatic steatosis (6 papers, 2021 to 2025). Steatosis is a term used to denote lipid accumulation within hepatocytes. "In the literature, LEAP-2 has been associated with hepatic steatosis, impacting the lipolytic/lipogenic pathway and insulin signaling in mice and humans." (PMID 41226108, 2025). "This study investigates the hypothesis that higher levels of LEAP-2 are associated with hepatic steatosis and the role of LEAP-2 serum levels in the earlier and easier diagnosis of MASLD in children." (PMID 41226108, 2025). "Elevated levels of LEAP-2 were found in mice and humans with liver steatosis and showed a positive correlation with fasting insulin, Homeostatic Model Assessment of Insulin Resistance, and liver fat content related to glucolipid metabolism." (PMID 38778244, 2024). "The plasma LEAP2 levels were reported to be positively correlated with age, BMI, and fasting insulin in patients with hepatic steatosis, but negatively correlated with acyl ghrelin." (PMID 35521798, 2022). "In mice rendered obese by HFD, LEAP2 overexpression in the ARC also reduced hepatic steatosis, improved glucose tolerance, and decreased plasma total cholesterol level." (PMID 36387867, 2022). "Elevated GH level following LEAP-2 knockdown promotes lipolysis and inhibits lipogenesis, thereby alleviates hepatic steatosis." (PMID 34512549, 2021). "The result showed that hepatic steatosis was relieved following the reduction in LEAP-2 level, which resulted from alterations in lipolytic and lipogenic gene expression as well as improved insulin sensitivity." (PMID 34512549, 2021). "Also, serum LEAP-2 levels were higher in adolescents with MASLD and are associated with CAP, AST, GGT, and total bilirubin, which are the parameters indicating the severity of hepatic steatosis." (PMID 41226108, 2025). "Firstly, long-term elevated expression of LEAP2 in the ARC reduces food intake, body weight, and adiposity with concomitantly improved hepatic steatosis, glucose tolerance, and blood lipids in mice exposed to HFD." (PMID 36387867, 2022).
type 2 diabetes (6 papers, 2022 to 2026). "In a study, LEAP2 was positively correlated with HbA1c parameter, with suggests LEAP2’s association with type 2 diabetes." (PMID 39796232, 2025). "The anorectic properties of LEAP2 might be very helpful in type 2 diabetes as this hormone might also affect insulin production." (PMID 39796232, 2025). "Studies have shown that LEAP2 has an impact on insulin secretion, suggesting its potential involvement in glucose metabolism and possibly insulin sensitivity, which is crucial in managing conditions like type 2 diabetes." (PMID 39796232, 2025). "The reduction in serum ghrelin levels and the elevation of Leap2 levels in individuals with type 2 diabetes may represent a physiological compensation as a response to a positive energy balance to maintain a normal energy balance." (PMID 36936164, 2023).
Anxiety (4 papers, 2022 to 2024). Intense feelings of nervousness, tension, or panic often arise in response to interpersonal stresses. "Here, we analyzed the effects of CNO (3 mg/kg, i.p.)co-injected with aCSF or LEAP2 (10 nM, i.c.v.)on anxiety-like behaviors in these mice." (PMID 36387867, 2022). "We also analyzed spontaneous locomotion activity, anxiety, and depression-like behaviors of mice overexpressing LEAP2 in ARC in the open field, elevated plus maze, tail suspension, and forced swimming tests." (PMID 36387867, 2022). "In order to determine whether activation of GHSR in the LC was necessary for feeding and anxiety behavior control, we utilized liver-expressed antimicrobial peptide 2 (LEAP2), a newly identified endogenous GHSR antagonist." (PMID 38026980, 2023). "To determine if ghrelin signaling in the LC is necessary for anxiety-like behavior, we exposed fasted rats to the OF and ASR tests after LEAP2 administration." (PMID 38026980, 2023). "The sex-divergent effect of LEAP2 is not surprising, as sex differences in ghrelin responses are apparent in relation to both feeding behaviors and for example anxiety-like behavior." (PMID 39358354, 2024). "Therefore, LEAP2 did not have an effect on anxiety-like behavior in the OF after adjusting for locomotion, in either sex." (PMID 38026980, 2023).
Insulin resistance (4 papers, 2024 to 2026). Increased resistance towards insulin, that is, diminished effectiveness of insulin in reducing blood glucose levels. "Absolute/decreases in fasting plasma LEAP2 positively correlated with absolute/decreases in body mass index, glycated hemoglobin A1c, fasting plasma glucose, serum insulin, homeostatic model assessment for insulin resistance, and serum triglycerides." (PMID 39659543, 2024). "However, it cannot be excluded that the decreases in fasting plasma LEAP2 are due to improvement in glycemic control, metabolic syndrome, and insulin resistance." (PMID 39659543, 2024).
bacterial meningitis (3 papers, 2021 to 2025). Inflammation of the membranes surrounding the brain and spinal cord due to a bacterial infection. "Given that increased CSF LEAP2 levels are specific for bacterial meningitis, CSF LEAP2 measurement may be useful as an auxiliary diagnostic measure." (PMID 33811478, 2021). "During bacterial meningitis, human cerebrospinal fluid shows an increase in LEAP2 concentration compared to control groups and groups suffering from other neurological diseases, and this concentration drops twofold after antibiotic treatment." (PMID 39796232, 2025). "In this study, we showed that patients with bacterial meningitis had significantly higher CSF LEAP2 concentrations than those with other neurological disorders and a control group." (PMID 33811478, 2021). "The CSF LEAP2 concentration was lower in the bacteremia patient (2.53 ng/ml) than in the five patients with bacterial meningitis (ranging from 4.51 ng/ml to 13.40 ng/ml; mean ± SD, 9.32 ± 3.76 ng/ml)." (PMID 33811478, 2021). "CSF LEAP2 is increased in patients with bacterial meningitis, suggesting its biological significance in the pathology of CNS infections." (PMID 33811478, 2021). "CSF LEAP2 concentrations in the bacterial meningitis group were significantly higher than those in the other four clinical groups." (PMID 33811478, 2021). "This shows that LEAP2 could be potentially used as a biomarker of diseases such as bacterial meningitis or rheumatoid arthritis." (PMID 39796232, 2025). "The elevated level of CSF LEAP2 in bacterial meningitis suggests that the molecule may play a role in some brain areas that regulate food intake and may mediate appetite reduction under inflammatory states." (PMID 33811478, 2021). "Considering LEAP2’s functions as an antimicrobial peptide and an antagonist of the ghrelin receptor, elevated CSF LEAP2 concentrations in bacterial meningitis suggest that LEAP2 may act against local bacterial infection or acute inflammation." (PMID 33811478, 2021). "In response to bacterial infection, LEAP-2 is induced in the liver, small intestine, immune tissues (e.g., bone marrow and tonsil), as well as cerebrospinal fluid (CSF) of patients with bacterial meningitis." (PMID 34512549, 2021). "Similarly, CSF LEAP-2 level also had a positive correlation with inflammatory parameters in patients with bacterial meningitis." (PMID 34512549, 2021). "Levels of LEAP2 were increased in the CSF of patients with bacterial meningitis." (PMID 33811478, 2021). "LEAP2 may have potential as a biomarker for bacterial meningitis." (PMID 33811478, 2021).
polycystic ovary syndrome (3 papers, 2021 to 2025). A disorder that manifests as multiple cysts on the ovaries. "It is recommended to conduct gender-specific research on women as studies have shown that LEAP2 plasma levels may be decreased in women with polycystic ovary syndrome (PCOS)." (PMID 39796232, 2025). "LEAP-2 is reported to be associated with two obese-related diseases, including non-alcoholic fatty liver disease (NAFLD) and polycystic ovary syndrome (PCOS)." (PMID 34512549, 2021).
rheumatoid arthritis (3 papers, 2020 to 2023). A chronic, systemic autoimmune disorder characterized by inflammation in the synovial membranes and articular surfaces. "This evidence indicates that LEAP2 is associated with inflammatory mediators in rheumatoid arthritis." (PMID 37317103, 2023). "Although plasma LEAP2 concentrations in patients with rheumatoid arthritis were reported to be higher than those in healthy subjects, the role of LEAP2 in inflammation has not yet been clarified." (PMID 33811478, 2021).